CXCR4 (C-X-C motif chemokine receptor 4)
Diseases named in the same sentence as CXCR4 in open-access papers (continued):
Sharing a sentence is not in itself a finding about the gene and the disease.
breast carcinoma (continued). "Chemokine (C-X-C motif) receptor 4 (CXCR4) has been reported as a poor prognostic biomarker in human breast cancers, and has been suggested as a promising therapeutic target of breast cancer treatment." (PMID 28446538, 2017). "Breast cancer cells expressing chemokine receptors CXCR4 and CCR7 were stimulated with appropriate chemokine receptor ligands CCL12 and CCL21 leading to pseudopodia formation and higher invasiveness." (PMID 28785589, 2017). "While CXCR4 is expressed in many cancers including breast cancer, melanoma, and colorectal cancer, little is known about the regulation of its ligand, CXCL12." (PMID 29037250, 2017). "The chitosan nanoparticle delivered siRNA efficiently into breast cancer MCF-7 cells significantly reduced the expression of CXCR4 in both mRNA and protein levels." (PMID 28446538, 2017). "The SDF-1/CXCR4 signaling pathway is involved in the growth and proliferation of breast cancer cells." (PMID 28402272, 2017). "High CXCR4 overexpression from breast cancer patients receiving neoadjuvant chemotherapy was predictive of poorer prognosis." (PMID 28415580, 2017). "In the present study, we investigated the delivery efficiency of siRNA by chitosan into breast cancer cells, and examined the regulatory role by chitosan nanoparticle-delivered siRNA on CXCR4 expression and on the chemosensitivity of breast cancer cells." (PMID 28446538, 2017). "Our results present the treatment potential of chitosan nanoparticle-delivered siRNA targeting CXCR4 in breast cancers." (PMID 28446538, 2017). "Taken together, our results present the treatment potential of chitosan nanoparticle-delivered siRNA targeting CXCR4 in breast cancers." (PMID 28446538, 2017). "First, we examined the expression of CXCR4 in a murine breast cancer cell line (4T1), HUVECs and a murine stromal cell line (MS-5)." (PMID 29263923, 2017). "It has been reported that CXCR4 is not only correlated with the metastatic spread of breast cancer cells, but also crucial in the tumor dissemination." (PMID 28446538, 2017). "Immunohistochemical analysis confirmed that BAG3 and CXCR4 intensities were positively correlated in most breast cancer specimens." (PMID 28703799, 2017). "In breast cancer, chemokine receptors such as CXCR4 and CCR7 play a critical role in determining the metastatic destination of tumor cells." (PMID 29155879, 2017). "In this study, we demonstrated the significant inhibitory effects of a novel chemically synthetic peptide (E5) on the CXCR4/CXCL12 axis in breast cancer both in vitro and in vivo." (PMID 29263923, 2017). "In conclusion, our results present the treatment potential of chitosan nanoparticle-delivered siRNA targeting CXCR4 in breast cancers." (PMID 28446538, 2017). "Analysis of patient outcome demonstrated that high CXCR4 expression predicted poor overall survival of patients with breast cancer." (PMID 28703799, 2017). "Further, in vivo neutralization of the CXCL12/CXCR4 interaction in breast cancer has been shown to significantly inhibit lung and lymph node metastasis." (PMID 28055968, 2017). "The chemokine system CXCL12/CXCR4 crucially regulates metastatic dissemination of breast cancer cells." (PMID 29100413, 2017). "Consistent with mRNA expression, western blot demonstrated that forced BAG3 expression increased CXCR4 protein levels in breast cancer cells." (PMID 28703799, 2017). "GRK3 is a critical determinant of cellular responses to proliferative and migration signals through CXCL12/CXCR4 in breast cancer." (PMID 29445249, 2017). "miR-29a can suppress tristetraprolin and can alter CXCR4 mRNA stability and CXCR4 protein expression, thereby increasing breast cancer EMT and metastasis." (PMID 28427228, 2017). "BAG3 was also found to be positively correlated with CXCR4 expression and unfavorable prognosis in patients with breast cancer." (PMID 28703799, 2017).
breast carcinoma (continued). "To further investigate the importance of chemokines CXCL12 and CXCL16 secreted by metastatic CAFs on breast cancer cell migration, we analyzed the expression of cognate chemokine receptors CXCR4 and CXCR6 on patient-derived cancer cells." (PMID 28649646, 2017). "Here, we report an interaction between CXCR4 and PDGFRα in promoting chemoresistance in breast cancer cells." (PMID 28415580, 2017). "For example, the systemic delivery of a vaccinia OV armed with a CXCR4 antagonist to mice with orthotopic mammary tumours disrupted the interaction between tumour cell CXCR4 and CXCL-12 present in the stromal microenvironment." (PMID 29157300, 2017). "Here we report a novel signaling from KLF8 to C-X-C cytokine receptor type 4 (CXCR4) in breast cancer." (PMID 26993780, 2016). "This was first demonstrated in breast cancer cells, where signaling through CXCR4 was shown to mediate actin polymerization and pseudopodia formation, and induce chemotactic and invasive responses." (PMID 27618899, 2016). "Target genes of GLI1 are induced, leading to contribute the cellular properties, such as the proliferation (by AEBP1) and metastasis (by CXCR4) of breast cancer cells." (PMID 26744317, 2016). "In one study, treatment with conditioned medium from the breast cancer cell line SUM102 elevated levels of CXCR4 in CAFs." (PMID 27782035, 2016). "The metastatic potential of breast cancer cells is acutely sensitive to regulation of the CXCL12/CXCR4 signaling axis governed by receptor expression, desensitization, internalization, and recycling dynamics." (PMID 27049755, 2016). "Overall, these findings clearly demonstrated that ligand-activated PPARγ by binding to a newly identified PPRE motif within the CXCR4 promoter downregulates CXCR4 expression levels in human breast cancer cells." (PMID 27556298, 2016). "Given the largely documented role of SDF-1α/CXCR4 axis in modulating cancer cell migration, we next assessed the ability of PPARγ agonist to influence cell migration and invasion of both breast cancer cells." (PMID 27556298, 2016). "In preclinical mouse models, antagonists or neutralizing antibodies of CXCL12/CXCR4 axis as potential therapeutic reagents have been shown to reduce LN metastasis of breast cancer cells and melanoma cells." (PMID 28036019, 2016). "When an inhibitory factor for BMP-4 was added to the co-cultures, migration of breast cancer cells was decreased and their CXCR-4 expression downregulated, demonstrating that BMP-4 acted as an activator of the CXCR-4/CXCL-12 pathway." (PMID 27571063, 2016). "In breast cancer, it was also found that targeting CXCR4 using artificial miRNA blocked the invasion and metastasis of breast cancer cells." (PMID 26759750, 2016). "CXCR4, which is expressed in malignant breast tumours and human breast cancer cells have been shown to play a major role in site-specific metastasis of breast cancers to the bone." (PMID 27590724, 2016). "Here, we have identified, for the first time, a functional PPAR responsive element within the CXCR4 promoter that is responsible of the PPARγ-mediated inhibition of CXCR4 expression in breast cancer cells." (PMID 27556298, 2016). "In a transgenic breast cancer mouse model, treatment with the CXCR4 inhibition CTCE-9908 resulted in a 56 % reduction in primary tumor growth rate compared to controls receiving scrambled protein." (PMID 26920352, 2016). "The direct involvement of SMRT in the CXCR4 promoter responsiveness to the BRL has been demonstrated after RNAi-mediated inhibition of this corepressor in breast cancer cells." (PMID 27556298, 2016). "Here, we identified a novel PPARγ-mediated mechanism that negatively regulates CXCR4 expression in both epithelial and stromal breast cancer cells." (PMID 27556298, 2016).
breast carcinoma (continued). "One important pathway that has been shown to be involved in breast cancer dissemination to distant organs is the CXCL12/CXCR4 axis; however, in our brain metastasis models neither of these genes showed significant changes." (PMID 27447568, 2016). "Enhanced CXCR4 expression on different tumor cells, such as non-small cell lung cancer, breast cancer, oral squamous cell carcinoma and neuroblastoma is associated with aggressive metastatic behavior." (PMID 27835905, 2016). "CXCL12 is highly expressed at common sites of breast cancer metastasis, such as the lymph nodes, liver, bone marrow, and lungs, and CXCR4 on tumor cells is critical for growth and migration." (PMID 27049755, 2016). "Breast carcinoma cells also express chemokine receptors, such as CXCR4, while metastatic cells in the liver express CXCL12, the ligand of CXCR4." (PMID 28105072, 2016). "To test if KLF8 and CXCR4 are co-overexpressed in patient tumors, we performed immunohistochemical (IHC) staining for CXCR4 in a human breast cancer tissue microarray in which KLF8 expression was determined previously." (PMID 26993780, 2016). "The use of highly specific inhibitors of E-selectin inhibited entry of breast cancer cells into the vascular niche, whereas inhibition of the CXCR-4/CXCL-12 axis induced mobilisation of dormant breast cancer cells from the vascular niche into circulation." (PMID 27782035, 2016). "In the same manner, overexpression of CXCR4 in breast cancer cell lines increased bone metastasis formation in animal models." (PMID 27782035, 2016). "Nevertheless, it will be important to determine the detailed signaling mechanisms that operate the critical feed-forward wheel of KLF8/CXCR4/FAK in breast cancer cells." (PMID 26993780, 2016). "Taken together, our results support a critical role of CXCR4 engagement by CXCL12 downstream of KLF8 for breast cancer metastasis." (PMID 26993780, 2016). "We do not know how FAK is activated by the feed-forward loop of KLF8/CXCR4 in response to CXCL12 stimulation in the breast cancer cells used in this study." (PMID 26993780, 2016). "Stromal Derived Factor-1α (SDF-1α) and its cognate receptor CXCR4 play a key role in mediating breast cancer cell invasion and metastasis." (PMID 27556298, 2016). "Among these candidates, the chemokine receptor CXCR4 has been well documented as a mediator of metastasis in breast cancer and CXCR4-overexpressing subpopulation of cancer stem cells was reported to be essential for tumor metastasis." (PMID 26870956, 2016). "Our data emphasize the functional relationship of GRK3 as it pertains to CXCL12/CXCR4 migration in breast cancer and specific molecular subtypes." (PMID 27049755, 2016). "Given the key role for both FAK and CXCR4 in breast cancer metastasis, FAK- and CXCR4-targeted therapies have been explored in pre-clinical tests and clinical trials." (PMID 26993780, 2016). "This activation causes an increased CXCR4 expression and subsequent feed-forward activation of FAK, resulting in CXCR4/CXCL12-dependent increase in migration, invasion, TEM and metastasis of breast cancer cells." (PMID 26993780, 2016). "For example, while CXCR4 is not found in normal breast tissues, it is rather overexpressed in breast cancer cells and a marked inhibition of breast cancer metastatic spread is achieved by inhibiting CXCR4." (PMID 27529230, 2016). "Others have proposed CXCR4 signaling and regulatory pathways as an attractive target for breast cancer treatment." (PMID 27049755, 2016). "We have confirmed that CXCR4, a marker and mediator of breast-cancer metastasis, is a target for repression by NCoR and TRβ." (PMID 27806339, 2016). "CXCR4 was shown to act as a chemoattractant that promotes invasion and migration in breast cancer cells." (PMID 26894969, 2016).
breast carcinoma (continued). "To investigate the role of activated PPARγ in the context of heterotypic signaling working in tumor-stroma interactions, we examined the ability of BRL to reduce CAF-induced effects through CXCR4 axis inhibition in breast cancer cells." (PMID 27556298, 2016). "Namely, breast cancer cells that express CXCR4 frequently metastasize to the lung, liver, lymph node and bone marrow where CXCL12 is expressed at high levels." (PMID 27136535, 2016). "Recently, CXCL12 (stromal cell-derived factor-1, SDF-1)/CXCR4 system has been reported to be involved the establishment of LN metastasis in different cancers, e.g., breast cancer and SCC, and ovarian cancer." (PMID 28036019, 2016). "CXC-chemokine receptor 4 (CXCR4) belongs to the G-protein coupled receptor group and is regularly involved in breast cancer metastasis." (PMID 26922065, 2016). "The data we present offers a mechanistic explanation for the role of CXCR4 signaling in breast cancer metastasis." (PMID 27049755, 2016). "The chemokine/receptor pair SDF-1/CXCR4 has been involved in the regulation of metastization of neoplastic cells, including human breast cancer." (PMID 29056725, 2016). "In this study, we showed that ANGPTL2 significantly up-regulated CXCR4 expression in breast cancer cells, which likely enhances their responsiveness to CXCL12." (PMID 25773070, 2015). "Experimental metastatic mouse models have shown that targeting or silencing CXCR4 inhibited development of metastasis in breast cancer." (PMID 26231656, 2015). "CD24 plays a role in facilitating metastasis by the interaction between tumor cells and platelets or endothelial cells and is also associated with proliferation, adhesion and invasion in MCF-7 breast cancer cells affecting their CXCR4 function." (PMID 26405647, 2015). "In this study, we investigated a novel biphenyl urea derivate, TPD7 for its ability to affect CXCR4 expression as well as function in breast cancer cells." (PMID 25753200, 2015). "Our previous studies indicated that CXCR4 was expressed more frequently in the TNBC than in other subtypes breast cancer." (PMID 25544759, 2015). "Earlier works demonstrated the regulatory effects of stromal derived factors on CXCR4 using mouse derived stromal cells in breast cancer." (PMID 25774696, 2015). "The rate of breast cancer specific mortality was higher in patients with both high phosphorylated-CXCR4 expression and low plasma CXCL12 levels than either low plasma CXCL12 or high phosphorylated-CXCR4 expression alone." (PMID 26161302, 2015). "This tissue-specific metastasis has been explained in part by the expression of CXCR4 and its downstream signaling of breast cancer cells." (PMID 26413813, 2015). "The observed inhibition of SDF-1-induced migration of TRAIL-R2 knockdown cells was most likely due to the significantly decreased levels of CXCR4 in these cells, previously shown to play a critical role in breast cancer metastasis." (PMID 25909161, 2015). "CXCR4 overexpression was associated with both PFS and OS in seven subtypes of cancers (hematological malignancy, breast cancer, colorectal cancer, esophageal cancer, renal cancer, gynecologic cancer, and liver cancer)." (PMID 25669980, 2015). "Our previous studies indicated that CXCR4 silencing affects the proliferation of breast cancer cells compared with parental cells." (PMID 25544759, 2015). "Reportedly, CXCR7 modulates CXCR4 signaling and enhances CXCL12-induced cell migration and metastasis of breast cancer cells, and LCP1 is implicated in the CXCL12-induced migration of chronic lymphocytic leukemia cells." (PMID 26413813, 2015). "We also observed that TPD7 suppressed the ligand induced invasion of breast cancers, and this correlated with the down-regulation of CXCR4." (PMID 25753200, 2015). "Müller and co-workers were the first to demonstrate CXCR4-mediated metastasis of breast cancer cells to CXCL12-rich environments, like bone marrow, brain, lungs and liver." (PMID 26396176, 2015).
breast carcinoma (continued). "Consistently with this, the up-regulation of CXCR4 in breast cancer cells has been clinically correlated with the distant metastasis and unfavorable overall survival of breast cancer." (PMID 26413813, 2015). "Hiller and Chu demonstrated that CXCR4 is important in several types of cancer, including breast cancer, and revealed that CXCR4 was highly expressed in areas common for breast cancer metastasis, including the axillary lymph nodes." (PMID 25901761, 2015). "Previously, an inhibiting peptide or a blocking anti-CXCR4 monoclonal antibody were used to specifically inhibit metastasis to the lungs in breast cancer models." (PMID 26622806, 2015). "It has also been reported that CXCL12/CXCR4 signaling induces actin polymerization and chemotactic property of breast cancer cells." (PMID 26055698, 2015). "Breast cancer cells, with upregulated CXCR4 genes, have been found engrossed to CXCL12 expressing cells in the lymph nodes, liver, and lungs, thus causing metastasis of disconnected tumor cells." (PMID 25814785, 2015). "Several studies have demonstrated the involvement of CXCR4 in cell proliferation, migration, and metastasis of solid tumors in a variety of cancers, such as gastric cancer, breast cancer and colorectal cancer." (PMID 25544759, 2015). "The use of AMD3100 labeled with Gallium-68 in breast cancer-bearing mice demonstrated the potential of CXCR4 antagonists as imaging reagents on the one hand and reflects the significance of CXCR4 as a marker structure in cancer on the other hand." (PMID 25671300, 2015). "It has been demonstrated that CXCR4 is involved in the invasion and metastasis of several types of cancer, including breast carcinoma." (PMID 25901761, 2015). "The up-regulation of CXCR4 is a key to enhancing the CXCL12-dependent migration of breast cancer cells." (PMID 26413813, 2015). "In established cellular models of human prostate and breast cancer, androgens and estrogens engage the CXCR4/CXCR7 axis by stimulating or inhibiting CXCR4 and CXCR7 expression, respectively." (PMID 25884570, 2015). "Breast cancer cells express several chemokine receptors that initiate liver metastasis, of which C-X-C Chemokine Receptor type 4 (CXCR4) is the most common." (PMID 25885919, 2015). "We here present evidence that GLI1 up-regulates the expression of CXCR4, CXCR7 as well as LCP1/L-PLASTIN, an actin-binding protein crucial for CXCL12/CXCR4 signaling, in breast cancer cells." (PMID 26413813, 2015). "One of the key points on describing the role of the CXCR4/CXCL12 axis in breast cancer pathogenesis is concerned with the IHC analysis of only CXCR4, once limited information on CXCL12 expression has been published." (PMID 26161302, 2015). "In the present studies, we investigated the effect of TPD7 (N-(4′-acetyl-3′,5,6-trimethoxybiphenyl-3-yl)-N′-[4-(3-morpholin-4-ylpropoxy)phenyl]urea) as a novel regulator of CXCR4 expression and function in breast cancer." (PMID 25753200, 2015). "The most studied role for CXCL12 chemokine and its receptor CXCR4 in breast cancer pathogenesis is the metastasis event, although several reports have demonstrated its involvement in other processes, such as angiogenesis and tumor growth." (PMID 26161302, 2015). "It has also been experimentally confirmed that the CXCR4 up-regulation enhanced the chemoattraction or directional migration of breast cancer cells to CXCL12 in vitro, as well as the lung metastasis in vivo." (PMID 26413813, 2015). "Activation of Ahr by 3,3′-diindolylmethane (DIM) suppresses breast cancer through repression of CXCR4 and/or CXCL12, and thereby, lowering the invasive and metastatic potential of MDA-MB-231 and MCF-7 cell." (PMID 26377202, 2015). "Here, we show that tumor cell-derived angiopoietin-like protein 2 (ANGPTL2) increases responsiveness of breast cancer cells to CXCL12 by promoting up-regulation of CXCR4 in those cells." (PMID 25773070, 2015).